IL18 (interleukin 18)
Diseases named in the same sentence as IL18 in open-access papers (continued):
Sharing a sentence is not in itself a finding about the gene and the disease.
Listeria infection (7 papers, 2018 to 2024). "There is additional evidence that NLRP6 played a role in exacerbating the symptoms of systemic listeriosis by boosting the expression of IL-18." (PMID 36556283, 2022). "Of note, in vivo treatment of mice with IL-12 and IL-18 on days 4–6 of Listeria infection reconstituted cytotoxic T cell response of aged mice to the level of adult." (PMID 31620129, 2019). "While IL-12, IL-6 and IFNγ are all inducible by TNF, IL-18 is a cytokine upstream of TNF that has been described as playing a role in protection from Listeria infection." (PMID 29438281, 2018). "The reconstitution of IL-18 caused an outrageous outcome in Nlrp6−/− and Casp 11−/− mice by Listeria infection, suggesting that the involvement of IFN-I and caspase 11 in the production of IL-18 may worsen Listeria infection outcome." (PMID 34768828, 2021). "Recently, a new mechanism for IL-18 production by Listeria infection was reported." (PMID 30717382, 2019). "Listeria infection induces IL-18 production by inflammasome-dependent and -independent mechanisms." (PMID 30717382, 2019). "Similarly, VPA inhibited the production of IFN-γ by NK cells stimulated with IL-12 and IL-18, which is a crucial system for early IFN-γ production in listeriosis." (PMID 33082490, 2020).
malnutrition (7 papers, 2017 to 2022). Inadequate nutrition resulting from poor diet, malabsorption, or abnormal nutrient distribution. "In this study, the risk of malnutrition is positively and negatively associated with IL-8 and IL-18 levels, respectively." (PMID 34444668, 2021). "It is difficult to explain the lower IL-18 level in patients with malnutrition risk in comparison to the patients with proper nutrition." (PMID 32297262, 2020). "An inverse relationship was observed between IL-18 level and malnutrition risk; per increase of IL-18 by one [pg/ml], odds of malnutrition decreased by 0.5% (95% CI 0.991–0.999)." (PMID 32297262, 2020). "The risk of malnutrition was negatively associated with Il-18 level." (PMID 32297262, 2020). "Risk of malnutrition was negatively associated with Il-18(OR = 0.995; 95% CI 0.991–0.999)." (PMID 32297262, 2020). "The cause of decreased IL-18 levels in patients with AN cannot be explained only by malnutrition, and although the causal relationship is unknown, it is possible that these decreased levels persist because of the tendency of AN to become chronic." (PMID 30832404, 2019). "According to the fact that malnutrition and a loss of appetite in older subjects are mostly multifactorial, it is not surprising that IL-18 accounts for only 4% of the variance of appetite." (PMID 34444668, 2021). "We conclude that IL-18 seems to exert a significant impact on appetite in acutely ill older hospitalized patients and should, therefore, be considered as a potential target in the diagnosis, prevention and treatment of malnutrition." (PMID 34444668, 2021). "In this single-center cohort study, authors aimed to investigate which of the chosen inflammatory markers (leptin, IL-18, IL-6, IL-1α, TNFα) may contribute to malnutrition and its consequences the most, and further reflected upon possible interventions, based on the most up-to-date literature." (PMID 36558477, 2022). "Although our study did not elucidate the role of IL-18 in the development of malnutrition and erythropoietin resistance in ESRD, we are sure it might be an interesting area for our future, larger studies." (PMID 36558477, 2022).
metastatic melanoma (7 papers, 2010 to 2024). A melanoma that has spread from its primary site to another anatomic site. "Finally, given that combined inhibition of BRAF/MEK is associated with improved clinical outcomes among patients with BRAF V600-mutated metastatic melanoma, we further assessed whether the addition of IL-18 to IL-15 was also able to rescue NK suppression induced by BRAF/MEK co-inhibition." (PMID 27563819, 2016). "The novel data obtained in this study support the use of IL-12 and IL-18 in combination for developing new therapeutic strategies for metastatic melanoma especially for patients with better survival rate and prognosis." (PMID 25889680, 2015). "While recombinant IL-18 has very limited therapeutic activity as a single agent in patients with metastatic melanoma, preclinical studies have shown that IL-18 binding protein inhibits hepatic and lung metastases in murine models." (PMID 21569399, 2011). "Third, resveratrol inhibited adhesion- and proliferation-stimulating effects of IL-18 on metastatic melanoma cells through hydrogen peroxide-dependent nuclear factor-kappaB translocation blockade on these cells." (PMID 21569399, 2011). "As IL-12 and IL-18 have important immunostimulatory role the aim of this study was to investigate their in vitro effects on functional and receptor characteristics of NK cells and their subsets in healthy controls (HC) and metastatic melanoma patients (MM)." (PMID 25889680, 2015). "So therapeutic strategies based on the adoptive transfer of IL-12 and IL-18 in combination preactivated NK cells might have an important place in immunotherapy of metastatic melanoma patients with better survival outcome and prognosis." (PMID 25889680, 2015). "Indeed, although IL-18 and IL-21 have not been evaluated in EOC patients, these cytokines as single agents showed limited clinical benefit in the setting of metastatic melanoma." (PMID 21203522, 2010).
non-small cell lung carcinoma (7 papers, 2021 to 2025). A group of at least three distinct histological types of lung cancer, including non-small cell squamous cell carcinoma, adenocarcinoma, and large cell carcinoma. "High levels of IL-18 were shown to be found in plasmas and tissue of immunotherapy-responding non-small cell lung cancer patients, and were linked to an antitumor immune gene signature and a reduced tumor burden." (PMID 37298187, 2023). "The NLRP3 inflammasome was found to be activated in non-small-cell lung cancer, promoting the release of IL-1β and IL-18." (PMID 39201564, 2024). "Accordingly, functional intratumoral CD8+ T cells were shown to express high levels of IL-18R in non-small cell lung cancer patients and were, furthermore, cytotoxic in the presence of IL-18." (PMID 37298187, 2023). "In lung cancer, particularly in Non-Small Cell Lung Cancer (NSCLC), TAMs in the TME play an important role because they are associated with the production of various pro-inflammatory cytokines and chemokines (IL-1β, IL-6, IL-8, IL-12, and IL-18), promoting tumor growth and metastasis." (PMID 41560727, 2025). "Eutilex Co., Ltd. in Korea engineered a combination of a targeted hepatocellular carcinoma tumor (HCC) marker, Glypican-3 (GPC3), and an IL-18-secreting CAR T cell therapy (EU-307 GPC3-IL18) which is in Phase I and designated for the treatment of HCC and non-small cell lung carcinoma." (PMID 39769266, 2024). "As for the role of IL-18 in predicting patients’ response to immunotherapy, it was shown that patients with non-small cell lung cancer who respond to treatment had lower levels of IL-18 compared to non-responders, which contrasts with other studies in the same tumor type." (PMID 37298187, 2023).
pulmonary TB (7 papers, 2012 to 2024). "AIM2 detects intracellular DNA, facilitating the release of pro-inflammatory cytokines IL-18 and IL-1β, which have been associated with protection against pulmonary tuberculosis (PTB)." (PMID 38935691, 2024). "This is supported by the previous findings that ATII cells produce IL-18 in primary lung tissue cultures from patients with pulmonary TB." (PMID 22570668, 2012). "Our results show that the IL-18 signalling complex may be exploited by M. tuberculosis to expand the clinical manifestation of pulmonary TB." (PMID 31821340, 2019). "Our results suggest that the IL-18 signalling complex might be exploited by M. tuberculosis to expand the clinical manifestations of pulmonary TB." (PMID 31821340, 2019). "The ATII cells and ATII-derived IL-18 might play a potential role in the pathomechanism of granulomatous in pulmonary TB." (PMID 22570668, 2012). "Therefore, direct analysis of serum components of the IL-18/IL-37 signalling complex and IP-10 may be applicable in designing novel rapid screening tests for pulmonary TB." (PMID 31821340, 2019). "This work aims to assess the level of expression of IL-18, IL-18BP, IL-18R, as well as IFN-γand IL-37 genes in patients with active pulmonary tuberculosis (ATB), healthy individuals with latent M.tb infection (LTB), and healthy uninfected controls (Control)." (PMID 32521630, 2020). "The role of IL-18, its binding protein IL-18BP, and IFN-γ in the development of the immune response against mycobacteria was confirmed by observing the increased level of the expression of these genes in the group of patients with active pulmonary TB." (PMID 32521630, 2020). "We performed a combined analysis of the proteins, free and total IL-18, IL-18BP, IL-37, IFN-γ in QFT supernatants and directly in serum samples from pulmonary TB patients and healthy individuals with or without latent M. tb infection to identify new markers for the diagnosis of ATB." (PMID 31821340, 2019).
respiratory failure (7 papers, 2016 to 2025). The significant impairment of gas exchange within the lungs resulting in hypoxia, hypercarbia, or both, to the extent that organ tissue perfusion is severely compromised. "IL-18 plasma levels were positively correlated with renal and respiratory failure in AP patients." (PMID 38256335, 2023). "Patients requiring respiratory failure showed depressed CD27, CXCL1, CXCL13, Gal-1, Gal-9, HO-1, IL-18, LAMP3, MCP-3, TNFRS12A." (PMID 34608231, 2021). "Such IL-1β, IL-18, and IL-33 were common inflammatory factors, our study showed that all of these could be increased during P-ALI, and even leading to respiratory failure." (PMID 38826806, 2024). "The serum sICAM-1and IL-18 levels in AECOPD patients with respiratory failure were higher than those in patients without respiratory failure, indicating that the sICAM-1 and IL-18 levels reflect COPD severity." (PMID 30792261, 2019). "Among 38 patients with acute respiratory failure, those with ARDS had significantly higher serum levels of IL-18, and serum IL-18 was significantly higher in nonsurvivors." (PMID 26980924, 2016).
sarcoma (7 papers, 2011 to 2025). A usually aggressive malignant neoplasm of the soft tissue or bone. "IGF1R CAR T cells produced higher amounts of IL-6 and IL-18 than ROR1 CAR T cells in response to certain sarcoma lines." (PMID 26173023, 2015). "Furthermore, sarcomas are known to be sensitive to NK cell activity, and IL-18 has been shown to enhance anti-tumor immunity in other NK cell-sensitive tumors, which may help explain our findings." (PMID 40386779, 2025). "Significant Cox regressions for IL18 expression were observed in five types of cancer, SKCM, SARC (sarcoma), BRCA (breast invasive carcinoma), LGG, and PAAD (P < 0.05)." (PMID 31731729, 2019).
ulcer (7 papers, 2019 to 2025). "In uninfected ulcer patients, NLRP3 expression correlated with IL-1β, whereas in infected groups, active caspase-1 was closely associated with both GSDMD-N and mature IL-18, supporting canonical pyroptosis activation." (PMID 40563885, 2025). "In contrast with control cohort, the amounts of IL-1β, IL-6, TNF-α, IL-18 in ulcer model cohort increased to 8.52-, 5.24-, 7.86-, and 4.16-folds, respectively." (PMID 34975497, 2021). "In addition, sodium butyrate significantly inhibited the mRNA levels of inflammatory factors such as tumor necrosis factor-α (TNF-α), interleukin-1β (IL-1β), interleukin-6 (IL-6), and interleukin-18 (IL-18) in the ulcer tissue." (PMID 40818135, 2025). "Also, increased mature IL-18 expression and low pro-IL-18 levels were the most common in the infected ulcer population (42.9% of the population)." (PMID 40563885, 2025). "To evaluate the anti-inflammatory effect of the CHRs on ulcers, we measured the levels of pro-inflammatory cytokines, including TNF-α, IL-6, IL-18, and IL-12 in the serum." (PMID 40283949, 2025). "mRNA levels of IL-1β, IL-6, IL-18, and TNF-α in the ulcer tissue were significantly reduced following butyrate treatment, while the levels of tight junction proteins Claudin-1 and ZO-1 were significantly elevated." (PMID 40818135, 2025).
unstable angina (7 papers, 2019 to 2025). "Observou-se que, em ambos os grupos, houve nítido aumento do risco de eventos cardiovasculares fatais de acordo com o valor médio da IL-18, porém o grupo dos pacientes com angina instável apresentou valor mais elevado desse marcador." (PMID 32491018, 2020). "Nesse estudo foram incluídos pacientes com angina estável ( n =855) e pacientes com angina instável ( n =373) e avaliado o valor preditivo da IL-18 em relação a morte cardiovascular." (PMID 32491018, 2020). "No grupo de pacientes com IAM, as concentrações médias de IL-18 também foram significativamente superiores às do grupo-controle (p<0,001) ou do grupo com angina estável (p<0,01)." (PMID 32491018, 2020). "Also, IL-18 concentration was significantly higher in patients with unstable angina compared to patients with stable angina." (PMID 31516856, 2019). "No grupo de pacientes com angina instável, as concentrações médias de IL-18 foram significativamente maiores do que no grupo-controle (p<0,001) ou no grupo com angina estável (p=0,001)." (PMID 32491018, 2020). "In the present study, nanocurcumin administration for 5 days to patients with unstable angina did not affect MPO, IL-18 and MMP-9 levels significantly." (PMID 31516856, 2019). "Results showed that administration of curcumin (80 mg/day) to patients with unstable angina was not able to reduce the level of MPO, IL-18 and MMP-9 biomarker." (PMID 31516856, 2019). "Results showed that administration of nanocurcumin (80 mg/day for five days) to patients with unstable angina could not reduce the level of MPO, IL-18 and MMP-9." (PMID 31516856, 2019).
vitiligo (7 papers, 2011 to 2025). Generalized well circumscribed patches of leukoderma that are generally distributed over symmetric body locations and is due to autoimmune destruction of melanocytes. "As our study showed high levels of serum IL‐1β and IL‐18 in vitiligo patients, activated dendritic cells in this disease can produce IL‐1β and IL‐18 in response to inflammatory stimuli." (PMID 39313936, 2024). "Genetic mutations in NLRP1 have been associated with hyperplasia and skin autoimmune disease like vitiligo accompanied with high levels of IL-1β and IL-18 detected in the serum of patients." (PMID 35428946, 2022). "However, our study showed increased levels of oxidative stress as well as IL‐1β and IL‐18 in vitiligo patients after using MBEHQ cream." (PMID 39313936, 2024). "Evidence suggest that proinflammatory cytokines such as interleukin‐1 (IL‐1) and interleukin‐18 (IL‐18) may be involved in the pathogenesis of vitiligo." (PMID 39313936, 2024). "Moreover, IL‐1β and IL‐18 can directly induce apoptosis (cell death) in melanocytes or disrupt their function, leading to depigmentation in vitiligo, which increased after using MBEHQ by vitiligo patients of this study." (PMID 39313936, 2024). "Relation between percentage of vitiligo (%) with (A) IL‐1β and IL‐18, (B) TOS, and MDA." (PMID 39313936, 2024). "As IL‐1β and IL‐18 are pro‐inflammatory cytokines in the autoimmune response in vitiligo, their increased blood levels after MBEHQ cream application may be due to increased ROS." (PMID 39313936, 2024). "Studies have shown that levels of IL‐1 and IL‐18 may be elevated in the skin of individuals with vitiligo." (PMID 39313936, 2024). "The exact mechanisms by which IL‐1 and IL‐18 contribute to vitiligo are still being investigated, but it is believed that these cytokines may play a role in triggering and perpetuating the autoimmune response that leads to melanocyte destruction." (PMID 39313936, 2024). "Overall, while the direct relationship between hydroquinone, MBEHQ, oxidative stress as well as IL‐1β, and IL‐18 with vitiligo is not well‐established, it is possible that these depigmenting agents could indirectly more stimulate the immune responses." (PMID 39313936, 2024).
Abdominal obesity (6 papers, 2018 to 2025). Excessive fat around the stomach and abdomen. "Stimuli including bad eating habits, increased abdominal obesity, sedentary lifestyle, smoking, and alcohol consumption increase the release of proinflammatory factors such as IL-6 and IL-18 from various tissues." (PMID 37736511, 2023). "In contrast, individuals with abdominal obesity cardiometabolically abnormal exhibited significantly higher levels of hs-CRP, IL-18, chemerin, and leptin, and lower levels of adiponectin and CAG-Ruminococcaceae compared to those with abdominal obesity cardiometabolically healthy and adequate waist." (PMID 39940942, 2025). "However, a study comparing EPA (2.7 g) and DHA (2.7 g) in individuals with abdominal obesity and low-grade systemic inflammation found lowering of CRP, IL-6, IL-18, and TNF, where DHA was more potent than EPA." (PMID 40058591, 2025).
acute liver failure (6 papers, 2013 to 2025). Rapid deterioration of liver function causing encephalopathy and coagulopathy. "Further studies are needed to study NK cell activation, cell signaling of the JAK-STAT pathways, cytokine secretion, such as IL-18, and IL-18BP, and degranulation in NBAS deficiency especially during fever-triggered acute liver failure." (PMID 34386911, 2021). "It is suggested that the trend of caspase-1 and IL-18 expression in the treatment can reflect the efficacy and prognosis of ALF to some extent; therefore, caspase-1 and IL-18 are expected to be predictors and future targets of acute liver failure." (PMID 24312909, 2013). "caspase-1 is an activating enzyme of IL-18, and the increase of these two proteins at the same time indicated that IL-18 in acute liver failure could be activated by Caspase-1 and thus played the role of induction of apoptosis." (PMID 24312909, 2013). "In vivo studies in different acute liver failure (ALF) animal models have shown the existence of cell death by necrosis resulted in rapid IL-1α precursor release and upregulation of IL-1β and IL-18, leading to tissue injury with massive upregulation of anti-inflammatory molecule IL-1Ra." (PMID 40529491, 2025). "Moreover, in human acute liver failure due to APAP overdosing, elevated levels of IL-18 are detectable in patients’ sera." (PMID 29472923, 2018).
age-related macular degeneration (6 papers, 2015 to 2022). Age-related loss of vision in the central portion of the retina (macula), secondary to retinal degeneration. "In the eye, IL-18 is currently being investigated as a potential therapeutic strategy for the treatment of age-related macular degeneration due to its strong anti-angiogenic actions." (PMID 25793779, 2015). "Increased expression of IL-1β and IL-18 is found in age-related macular degeneration (AMD), diabetic retinopathy, retinitis pigmentosa, and glaucoma." (PMID 35008812, 2021). "Studies focusing on age-related macular degeneration have also reported NLRP3-inflammasomes-dependent cytokine induction of IL-1β and IL-18, both locally and systemically." (PMID 34071438, 2021). "In patients with age-related macular degeneration (AMD), increased mRNA levels of NLRP3, IL-1β, and pro-IL-18 in lesions of the retinal pigment epithelium and photoreceptors were detected." (PMID 28273882, 2017).